DLEU7 (deleted in lymphocytic leukemia 7)
Synonyms: FLJ44882; LINC01308; DLEU1-AS1
Tractability: No criterion of Open Targets' tractability assessment is met for any kind of drug.
Gene: Protein-coding gene on chromosome 13 (50,519,364 to 50,843,939, reverse strand). Ensembl gene ENSG00000186047.
Genetic constraint (gnomAD): Loss-of-function variants: 17 observed, 11.89 expected, observed/expected ratio (o/e) 1.43, 90% interval 0.96 to 1.9. The upper end of that interval is the gene's LOEUF score, 1.9, which puts it in group 6 of 6, group 1 being the genes least tolerant of losing a copy. Missense variants: 308 observed, 241.02 expected, observed/expected ratio (o/e) 1.28, 90% interval 1.16 to 1.4. Synonymous variants: 113 observed, 96.11 expected, observed/expected ratio (o/e) 1.18, 90% interval 1.01 to 1.38.
Homologues: Orthologues: chimpanzee DLEU7 (100% identical), macaque DLEU7 (94% identical), rabbit DLEU7 (85% identical), rat Dleu7 (84% identical), mouse Dleu7 (83% identical), pig DLEU7 (80% identical), guinea pig DLEU7 (79% identical), tropical clawed frog dleu7 (34% identical).
Diseases named in the same sentence as DLEU7 in open-access papers:
DLEU7 is named in the same sentence as 11 diseases in open-access papers, as found by Europe PMC text mining. Sharing a sentence is not in itself a finding about the gene and the disease. The quoted sentences say what the papers report.
leukemia (4 papers, 2013 to 2022). A malignant (clonal) hematologic disorder, involving hematopoietic stem cells and characterized by the presence of primitive or atypical myeloid or lymphoid cells in the bone marrow and the blood. "Mosaic deletions of DLEU7 were observed 2 leukemia cases, 1 non-Hodgkin Lymphoma case and 4 individuals without a hematologic cancer." (PMID 23533652, 2013).
chronic lymphocytic leukemia (3 papers, 2013 to 2022). "Loss of the deleted in lymphocytic leukemia 7 (DLEU7) gene is frequently observed in chronic lymphocytic leukemia, due to hypermethylation of the DLEU7 promoter." (PMID 24963031, 2014). "Deletions of 13q were observed in 7 individuals with a minimally deleted region of 714 Kb that contains the DLEU7 gene, which is thought to play a role as a tumor suppressor in chronic lymphocytic leukemia." (PMID 23533652, 2013). "Since negative DLEU7 expression and hypermethylation of its promoter were previously found in patients with B-cell chronic lymphocytic leukemia (B-CLL), DLEU7 was previously proposed to be a candidate cancer suppressor gene in CLL located in 13q14." (PMID 35506368, 2022).
B-cell lymphoma (1 paper, 2022). "Interestingly, some of these genes, such as LEP, ALOX12, RARRES2, DLEU7, and FOXR1, have been reported to be associated with other hematologic malignancies, including AML, chronic lymphocytic leukemia (CLL), and B-cell lymphoma." (PMID 35847864, 2022).
tumor (2 papers, 2013 to 2023). "While DLEU7 is a protein-coding gene, DLEU1 was recently discovered to be part of a bigger gene, BCMS, that has a potential tumor-suppressing function." (PMID 36525587, 2023).
cardiovascular disease (1 paper, 2023). "DLEU7 is associated with cardiovascular disease and systolic blood pressure, whereas MSRB3 plays a relevant role in protein and lipid metabolism." (PMID 37328831, 2023).
DLEU7 also shares sentences with these, for which no sentence is quoted: cancer (2 papers); gastric cancer (1); hematologic cancer (1); hematologic malignancies (1); Hodgkins lymphoma (1); peripheral neuropathy (1).